AHR (aryl hydrocarbon receptor)
Diseases named in the same sentence as AHR in open-access papers (continued):
Sharing a sentence is not in itself a finding about the gene and the disease.
inflammatory bowel disease (continued). "Although the mechanism underlying this observation remains unknown, this study suggests that AHR agonists are targetable for the treatment of inflammatory bowel disease (IBD) and metabolic syndrome." (PMID 37394584, 2023). "The question of whether intestinal kaempferol metabolites or kaempferol itself can regulate the AhR and its specific effects within the gut is an area that requires attention to address urgent clinical issues, such as inflammatory bowel diseases." (PMID 37627637, 2023). "Decreased activation, as well as hyperactivation of AhR, may contribute to the pathogenesis of multiple human diseases such as inflammatory bowel disease, autoimmune disorders, and cancer." (PMID 36136583, 2022). "Tryptophan, an essential amino acid, and its catabolites have been suggested to affect intestinal homeostasis through the aryl hydrocarbon receptor and may be important in inflammatory bowel diseases." (PMID 36476263, 2022). "Interestingly, the association between AHR, IL10, and inflammatory bowel disease, together with 19 other TF–cytokine-disease associations was absent in predictions based on PDIs from the union of TRRUST and InnateDB." (PMID 30184180, 2018). "Low expression of the AhR is also found in inflammatory bowel disease." (PMID 27829840, 2016). "Our results support this hypothesis and suggest that AhR could be a new target for inflammatory bowel disease patient management." (PMID 24236236, 2013). "AhR also serves as a docking station for indole and downregulates intestinal inflammation, inflammatory bowel diseases (IBD), including Crohn’s disease and ulcerative colitis (UC), celiac disease, liver disease, and neurological diseases (reviewed by Dicks)." (PMID 41226575, 2025). "The aryl hydrocarbon receptor (AhR) and the peroxisome proliferator-activated receptor γ (PPARγ) are ligand-activated transcription factors that have in recent years been investigated for their anti-inflammatory properties for treatment of inflammatory bowel diseases (IBDs)." (PMID 39684781, 2024). "It has been shown that microbiome disruption leads to altered AHR signaling and worsened symptoms in inflammatory bowel disease (IBD) and metabolic syndrome." (PMID 38794769, 2024). "Spermidine exerts effective anti-inflammatory effects by increasing the intestinal mucosal barrier function via AhR in mice with experimental inflammatory bowel disease (IBD)." (PMID 39416781, 2024). "The AhR is extensively expressed in both immune and non-immune cells of the intestinal tract and its activation has been associated with the prognosis of intestinal conditions, including inflammatory bowel diseases." (PMID 37627637, 2023). "Many genes regulating Treg and Th17 cell differentiation are related to the pathogenesis of inflammatory bowel disease (IBD), and aryl hydrocarbon receptor (AhR) is one of them." (PMID 33082710, 2020). "Indeed, the expression of AHR is reduced in the lesioned intestine in inflammatory bowel diseases." (PMID 31683543, 2019). "Lack of AhR signaling has been implicated in the pathogenesis of inflammatory bowel disease." (PMID 24905458, 2014). "The aryl hydrocarbon receptor (AHR) is pivotal in the pathogenesis and treatment of inflammatory bowel disease (IBD) due to its diverse immunomodulatory effects, which include immune regulation, modulation of the gut microbiota, anti-inflammatory actions, and tissue repair." (PMID 39861130, 2025). "The tryptophan metabolites can contribute to the modulation of intestinal immune cells and barrier functions via activating aryl hydrocarbon receptor (AHR), which is involved in the inflammatory bowel disease (IBD) pathogenesis 121–123." (PMID 36919486, 2023). "Although SFB are generally not present in the human gut, these findings translate to human inflammatory bowel disease (IBD), where AhR expression is significantly downregulated and ILC1s accumulate in the inflamed ileum of patients with Crohn’s disease, at the expense of ILC3s." (PMID 36144238, 2022).
inflammatory bowel disease (continued). "Individuals with inflammatory bowel disease (IBD), metabolic syndrome or celiac disease have decreased fecal concentrations of AhR ligands and reduced AhR activity." (PMID 36296244, 2022). "AHR activation is involved in inflammatory bowel disease (IBD) among other diseases, and it is suggested that a reduction in bacterial tryptophan metabolism may contribute to IBD." (PMID 32178396, 2020). "Additional investigations in the context of chronic inflammation like inflammatory bowel disease (IBD) have shown that hypoxia and HIF-1α impair UCB-induced CD39 upregulation in Th17 cells that become less responsive to AhR activation." (PMID 33553158, 2020). "Regarding specifically the AhR-stimulating activity of coffee, this property may actually have favorable influences on health, because some dietary AhR ligands might be beneficial for the prevention and treatment of inflammatory bowel disease, metabolic syndrome, etc." (PMID 25007155, 2014). "Studies have shown that fecal AHR agonist activity and the concentrations of key indole ligands such as IAA are significantly reduced in patients with metabolic syndrome (MetS) and patients in remission of inflammatory bowel disease (IBD)." (PMID 41602107, 2026). "This review synthesizes current evidence on the interplay between the aryl hydrocarbon receptor (AhR), G protein-coupled receptor 35 (GPR35), cytochrome P450 enzymes, and dietary ligands in the context of inflammatory bowel disease (IBD) and colorectal cancer (CRC)." (PMID 41009721, 2025). "On the contrary, AhR-JAK/STAT crosstalk might have anti-inflammatory consequences, as in inflammatory bowel disease and central nervous system inflammation and neurodegeneration." (PMID 39211042, 2024). "We show that dietary supplementation with an AHR pre-ligand offers protection against inflammatory bowel disease in a mouse model while protection fails in mice lacking AHR in the intestinal epithelium." (PMID 37669965, 2023). "Additionally, the activation of the AHR was found to preserve the integrity of the epithelium and mitigate the disruption of cellular trans-epithelial electrical resistance (TEER) within the intestinal epithelial barrier in cases of inflammatory bowel disease." (PMID 39575260, 2024). "Gut disorders such, as inflammatory bowel disease (IBD), have increased dramatically in the past 50 years, driven by incompletely defined environmental factors including diet, with reduced intake of substances such as indole compounds, which function as aryl hydrocarbon receptor (AHR) ligands." (PMID 37944594, 2024). "There are currently no AhR agonists in clinical trials for cancer therapy; however, the activation of AhR by tryptophan is being explored clinically as a therapeutic approach for inflammatory bowel disease." (PMID 37106727, 2023). "The upregulation of AhR-Nrf2 pathway and its target gene HO-1 (also known as HSP32) expression enhances the barrier function in the mice with inflammatory bowel diseases (IBD)." (PMID 32168808, 2020). "In T helper type 17 (Th17) cells, BR exerts its immunomodulatory properties through AhR-dependent upregulation of CD39, with beneficial effects for patients with inflammatory bowel disease (IBD)." (PMID 32082323, 2020). "Likewise, another study demonstrated that indole-3-propionic acid (IPA)-mediated AhR activation led to reduced IFN-γ production by DCs and promoted IL-10 producing T-cell differentiation in inflammatory bowel disease (IBD) in mice." (PMID 39211042, 2024). "Similarly, mesalamine activates AHR, and enhances Tregs in the absence of modulation of Th1 and Th17 cells during inflammatory bowel disease, while treatment with 10-chloro-7H-benzimidazo[2,1-a]benzo[de]iso-quinolin-7-one (10-Cl-BBQ) diminishes Th17 cells but not Th1 cells in NOD mice." (PMID 29379138, 2018).
inflammatory bowel disease (continued). "Additionally, AhR is involved in the development of some chronic inflammatory diseases, such as inflammatory bowel diseases (IBD) and cancer development, so ESR-Ex may also help to treat AhR-mediated and NOX-mediated (via AhR activation) diseases." (PMID 35455428, 2022).
glioma (86 papers, 2013 to 2025). A benign or malignant brain and spinal cord tumor that arises from glial cells (astrocytes, oligodendrocytes, ependymal cells). "The occurrence of Crohn's disease was found to be associated with a mutation at the AhR gene rs2158041 in the Chinese population, whereas xeroderma, rheumatoid arthritis, glioma, and vitiligo have been associated with polymorphisms in the SNPs of the AhR gene." (PMID 41169884, 2025). "Because AhR is involved in the response to PAHs, genetic variants of AhR can increase the risk of glioma after exposure to PAHs." (PMID 32325928, 2020). "Two of the six AhR polymorphisms that have been studied, rs2066853 and rs2158041, are significantly associated with glioma risk and levels of PAH–DNA adducts in glioma tissue." (PMID 32325928, 2020). "TDO activity in gliomas has been linked to activation of the AhR and reduced antitumor immune responses." (PMID 25346733, 2014). "IL4I1 (part of our risk model) is able to activate AHR through the production of indole metabolites and canine, and is associated with decreased survival rate, promotion of cancer cell movement, and inhibition of adaptive immunity in people with glioma." (PMID 36407768, 2022). "Accordingly, AhR expression was shown to be associated with a poor prognosis in glioma." (PMID 33451095, 2021). "The generation of reactive oxygen species may have a role in the underlying MoA of AhR-mediated glioma, as well as the activation of glutamate receptors, histone acetylation, signal transducers, peroxisome proliferator-activated receptors, and transcription activators." (PMID 29487603, 2018). "TDO2 overexpression has been documented in gliomas, where it drives Trp metabolism to Kyn, activating the AhR and downstream PI3K/AKT signaling pathways to promote tumor stemness and growth." (PMID 41332472, 2025). "A study by Opitz, in 2011, detected that the constitutive activation of the AhR, driven by increased kynurenine (Kyn) production, has been shown to contribute to glioma malignancy and progression." (PMID 40149846, 2025). "There is strong evidence that dysregulated tryptophan metabolism in GBM promotes glioma progression via AhR activation and downstream signaling." (PMID 40149846, 2025). "AhR activation also facilitates EMT in gliomas through a transforming growth factor‐β‐dependent mechanism, increasing tumor invasiveness." (PMID 41332472, 2025). "IDO1 and TDO contribute to increased kynurenine production and AhR expression, which further regulate glioma cell migration and invasion." (PMID 40075568, 2025). "Our discovery of the opposite regulation of IL11 by ITE and kynurenine suggests that it is an AHR target in glioma." (PMID 40283908, 2025). "Studies highlight the role of the AhR in regulating cell mobility and demonstrate that inhibiting the AhR in glioma blocks the invasive activity of these cells." (PMID 40149846, 2025). "The fact that ITE, which is otherwise immune-suppressive, can activate immunity in glioma indicates that searching for drugs targeting AHR should go beyond antagonists." (PMID 40283908, 2025). "This study evaluated naringenin’s impact on glioma cells, with a focus on its potential to modulate AhR activity and the regulation of key inflammatory mediators involved in tumor proliferation, migration, and chemoresistance." (PMID 40149846, 2025). "Lastly, we determined that IL4I1, IDO1, and AHR are significantly higher in GBMs compared to low-grade gliomas." (PMID 38937431, 2024). "Along these lines, compounds stimulating AHR have been identified to beneficially affect innate and adaptive immunity and prevent tumor development in a variety of cancer types, including glioma, making AHR an appealing prospective therapeutic target." (PMID 38998940, 2024). "Reportedly, in glioma cells, aryl hydrocarbon receptor (AhR) is activated by kynurenine (Kyn), which is generated by indoleamine 2,3-dioxygenase (IDO), causing tumor-associated macrophage (TAM) accumulation in the TME." (PMID 38434684, 2024).
glioma (continued). "A potential route of microbial-derived tryptophan on glioma development is via the aryl hydrocarbon receptor(AHR), a ligand-activated transcription factor that plays a role in cell metabolism, proliferation, differentiation, cell death, and cell adhesion." (PMID 39594997, 2024). "Tryptophan metabolites activate the aryl hydrocarbon receptor (AHR) pathway, promoting tumor cell proliferation in gliomas, including astrocytomas, medulloblastomas, and glioblastomas." (PMID 39022732, 2024). "Another study revealed that the small molecule, methyl 2-(1H-indole-3-carbonyl)-thiazole-4-carboxylate (ITE), activates endogenous aromatic hydrocarbon receptors (AHR) and hinders various modes of glioma cell migration." (PMID 39149512, 2024). "AHR is also expressed in gliomas; therefore, the gut microbiota is critically involved in dietary tryptophan metabolism and catalyzes tryptophan to produce AHR agonists." (PMID 39594997, 2024). "AhR inhibition using pharmacological agents and gene silencing reduced clonogenic survival and invasiveness of glioma cells." (PMID 38068712, 2023). "Increased expression of AhR target genes involved in signaling pathways related to immune tolerance correlated with decreased survival in patients with glioma." (PMID 36900311, 2023). "Aryl hydrocarbon receptor (AhR) level had higher expression in patients with glioma than in healthy individuals." (PMID 38068712, 2023). "Analysis of the human glioma microarray dataset GSE4290 demonstrated a positive correlation between AhR expression and pathological glioma grade." (PMID 38068712, 2023). "We analyzed the TCGA database to examine IL4I1, IDO1, and AHR expression and their contribution to glioblastoma and low-grade glioma (LGG) patients’ clinical outcome." (PMID 37986881, 2023). "AhR expression in patients with all grades of glioma (grades II and III and GBM) was higher than that of patients without tumors and the level of expression correlated with the clinical grades, indicating the regulatory role of AhR in GBM." (PMID 38068712, 2023). "Combining TDO2 or AhR inhibitors with temozolomide has thus been proposed as an appealing alternative treatment for glioma patients." (PMID 35681770, 2022). "IDO1/TDO activated the Kynurenine-AHR signaling pathway, which was positively correlated with the pathological grade and Ki67 index of glioma as well as negatively correlated with overall survival." (PMID 36003766, 2022). "In conclusion, AHR is an important factor of the gut microbiome affecting the progression of glioma." (PMID 36003766, 2022). "Treatments with AhR antagonists have yielded promising results in rheumatoid arthritis and in cancers, e.g., melanoma and glioma." (PMID 35987825, 2022). "What’s more, by consuming endogenous tryptophan, glioma cells activate AHR and to inhibit T cell function, induce T cell apoptosis, promote CD39 expression, and induce the differentiation of T cells mediated by interleukin 10 (IL-10)." (PMID 36003766, 2022). "IL4I1 was positively correlated with AHR activity and negatively correlated with patient survival in both high-grade and low-grade gliomas." (PMID 36003766, 2022). "Subsequent analysis revealed that autocrine kynurenine in glioma cells activated the AHR pathway, resulting in an increase of cell survival and motility." (PMID 36188218, 2022). "On the other hand, Kyn secreted by glioma cells activated AHR in GAMs to inhibit the cytotoxicity of T lymphocytes by up-regulating the production of ectonucleotidase CD39 and adenosine." (PMID 34211978, 2021). "The tryptophan metabolite Kyn produced by glioma cells participates in its function by activating the AHR in GAMs." (PMID 34659216, 2021). "In a glioblastoma cell line-U87MG, inhibition of IDO1/TDO with RY103, Kyn-AhR mediated proliferation of glioma cells reduced that suggest Kyn-AhR involvement in pathology of glioblastomas." (PMID 34205235, 2021).